BMAL1 (basic helix-loop-helix ARNT like 1)
Diseases named in the same sentence as BMAL1 in open-access papers (continued):
Sharing a sentence is not in itself a finding about the gene and the disease.
glioma (continued). "Several core-clock genes have been reported to be dysregulated in gliomas, namely, CLOCK and BMAL1 were found to be overexpressed in high-grade glioma cells and GBM tissue, respectively." (PMID 37400829, 2023). "Circadian genes CLOCK and BMAL1 are found to regulate expression of IL-1ß and LDHA in gliomas, with suppression of CLOCK and BMAL1 leading to a reduction in LDHA and IL-1ß levels." (PMID 38173841, 2023). "Different from BMAL1 expression, HIF-1a expression in low-grade glioma tissues differs from that in adjacent peritumor tissues (P < 0.05)." (PMID 34815366, 2021). "In gliomas, the MVD of BMAL1− samples was 25.3 ± 10.93 and the MVD of and BMAL1+ samples was 43.75 ± 10.94, with a statistically significant difference (P < 0.05)." (PMID 34815366, 2021). "In our model, higher efficacy of 1A-116 was observed at circadian times of low BMAL1 expression in GBM cells and a differential overall survival was found when applying 1A-116 at ZT12 to glioma-bearing nude mice." (PMID 34371781, 2021). "The positive expression of BMAL1 protein in tumor tissues correlated with the distribution of high MVD, which was more obvious in high-grade glioma." (PMID 34815366, 2021). "In glioma cells, cell invasion was inhibited by BMAL1 overexpression through blocking of PI3K/AKT/matrix metalloproteinase-2 (MMP2) pathway where BMAL1 attenuates BCL-W oncogene that activates the invasion pathway." (PMID 32195174, 2020). "By analyzing the oscillations of clock-related genes (BMAL1 and PER2) and transferrin receptor levels in U87 glioma cells, we identified optimal timing for the complexes’ cellular uptake and payload delivery using two complementary computational tools (CircWave and CosinorPy)." (PMID 40649908, 2025). "MiR‐7239‐3p in M2 microglial exosomes, not M1 type, inhibits Bmal1 expression, promotes proliferation, and reduces apoptosis of glioma cells." (PMID 36066207, 2022). "The expression level of BMAL1 in glioma cells was significantly different from non-tumor brain cells (P < 0.05)." (PMID 34815366, 2021). "In humans with glioma of different pathological grades, BMAL1 expression was significantly different, and the expression of ANG2 (Angiopoietin 2) and VEGF (Vascular endothelial growth factor) was positively correlated with the expression of BMAL1." (PMID 34815366, 2021). "Our results showed that in gliomas co-cultured with M2 microglia, the expression of the BMAL1 protein was decreased (P < 0.01), while the expression of the CLOCK protein was increased (P < 0.05); opposite results were obtained in gliomas co-cultured with M1 microglia." (PMID 33528793, 2021). "BMAL1 was expressed at different levels in both glioma and normal tissues (non-tumor brain tissue specimens), and all the staining was observed in the nucleus." (PMID 34815366, 2021). "The expression of BMAL1 was detected in 74.68% (59/79) of glioma tissues, and 31 (39.24%) of the 79 non-tumor brain tissues were positive for BMAL1." (PMID 34815366, 2021). "BMAL1 expression was not different between WHO grade low-grade gliomas (I/II) and adjacent non-tumor tissues (P > 0.05)." (PMID 34815366, 2021). "Finally, we used the lentiviral transfection technique to stably down-regulate Bmal1 in GL261 cells and found that such down-regulation enhanced the proliferation and migration of glioma cells, which in turn, promoted the progress of glioma." (PMID 33528793, 2021). "The BMAL1 was expressed at significantly higher levels in high-grade glioma (III/IV) than in low-grade glioma (P < 0.001) and adjacent non-tumor tissues (P < 0.001)." (PMID 34815366, 2021). "The rhythm gene BMAL1 (Brain and Muscle ARNT-Like 1) may play an important role in glioma tolerance for anti-angiogenesis therapy." (PMID 34815366, 2021).
glioma (continued). "The expression of BMAL1 was shown to be positively correlated with the pro-angiogenic factors HIF1α (Hypoxia Induced Factor 1 alpha), VEGF (Vascular Endothelial Growth Factor), and ANG2 (Angiopoietin 2) in a cohort of 79 patients of high- and low-grade glioma (HGG and LGG)." (PMID 38378853, 2024). "Researchers have not determined whether BMAL1 regulates tumor biological behaviors by regulating angiogenesis in glioma." (PMID 34815366, 2021). "Therefore, BMAL1 likely participates in the angiogenesis of glioma by modulating ANG2 and VEGF expression, alters the therapeutic effect of anti-angiogenic treatments, and promotes peritumoral brain edema of glioma." (PMID 34815366, 2021). "Additionally, the expression of BMAL1 correlated with the pathological grade of glioma, but not with the patient's age, gender, or tumor size." (PMID 34815366, 2021). "Therefore, in this study, we examined the correlation between the expression of the BMAL1 gene and the expression of HIF-1a, ANG1, ANG2, and VEGF in human glioma tissues, as well as the relationships between the expression of the BMAL1 gene and the number of tumor microvessels and peritumor edema." (PMID 34815366, 2021). "Therefore, an examination of the regulatory effects of BMAL1 on the expression of the angiogenic factors ANG1 (Angiopoietin 1), ANG2, and VEGF in glioma will be conducive to understanding the reasons for glioma tolerance to vascular targeted therapy and the development of new target drugs." (PMID 34815366, 2021). "Similarly, in rat-1 fibroblast and C6 glioma cells, inhibition of p38 MAPK with SB203580 lengthened the period of the PER2::LUC reporter, and inhibition of U2OS cells with SB202190 lengthened the period of a Bmal1-dLuc reporter." (PMID 29316898, 2018). "Thus, in lung cancer and glioma cells, BMAL1 knockdown induced cancer cell invasion in parallel with activation of the PI3K/Akt/MMP2 pathway, whereas, in drug-resistant metastatic colorectal cancer, BMAL1 promotes expression of genes involved in angiogenesis and tumor progression." (PMID 34209857, 2021). "As it was reported for its binding partner BMAL1, TCGA database analysis revealed that the Clock gene, located at 4q12 chromosomal region, is amplified in ~5% of GBM patients, and high-grade gliomas exhibited an increased expression of CLOCK compared to low-grade glioma or non-tumor cells." (PMID 34361055, 2021).
colorectal cancer (40 papers, 2014 to 2025). A primary or metastatic malignant neoplasm that affects the colon or rectum. "One study has demonstrated an association between BMAL1 and resistance to bevacizumab in colorectal cancer." (PMID 38703241, 2024). "Gain‐ and loss‐of function analyses revealed that BMAL1 play a role in inducing proliferation and metastasis of colorectal cancer cells both in vitro and in vivo." (PMID 36806631, 2023). "BMAL1 has been shown to be associated with drug resistance of colorectal cancer cells via its regulation of VEGF." (PMID 37601651, 2023). "Since BMAL1 has been implicated in EMP of colorectal cancer cells, we employed Bmal1::Luc plasmid transfection into parental or clonal cultures of PANC-1 and measured circadian luminescence rhythms after synchronization with dexamethasone (dexa)." (PMID 35565186, 2022). "High BMAL1 expression in tumor cells was associated with poor clinical outcomes in patients with colorectal cancer receiving Beva (anti-VEGF) combined with chemotherapy." (PMID 34815366, 2021). "Other studies have confirmed that high BMAL1 expression is associated with increased sensitivity of colorectal cancer cells to oxaliplatin (DNA/RNA synthesis inhibitor) and predicts favorable outcomes for patients treated with oxaliplatin-based chemotherapy." (PMID 34977153, 2021). "BMAL1 disease-associated missense mutations are linked predominantly to large intestine cancer (D22N, S27Y, R37C, R37H, R244Q, and V260A)." (PMID 33799876, 2021). "For example, compared to healthy tissue, colorectal cancers (CRC) often display higher CLOCK or BMAL1 expression, which is associated with liver metastasis and poorly differentiated or late-stage CRC cancer." (PMID 32388500, 2020). "For example, disruption in the core clock protein BMAL1 results in severe premature aging and overexpression is associated with decreased overall survival, particularly in colorectal cancer patients." (PMID 27285754, 2016). "Similarly, in colorectal cancer cell lines, BMAL1 overexpression yielded comparable effects, and increased BMAL1 expression was associated with prolonged patient survival." (PMID 41142939, 2025). "Bmal1 knockout mice show a heightened susceptibility to colitis‐associated colorectal cancer." (PMID 38469551, 2024). "Moreover, high BMAL1 expression is associated with increased sensitivity of colorectal cancer cells to oxaliplatin in vitro and in vivo, and predicts favorable outcome for patients treated with oxaliplatin-based chemotherapy." (PMID 29946530, 2018). "In addition, in clinical samples from colitis-associated colorectal cancer patients, low expression of the Bmal1 gene in paracancerous tissues and tumor central regions was closely associated with a poorer prognosis in colitis-associated colorectal cancer patients." (PMID 35320972, 2022). "Similarly, Bmal1 overexpression increases the response of colorectal cancer to oxaliplatin in vitro and in vivo and its high expression levels are associated with better outcomes in colorectal cancer patients." (PMID 33114496, 2020). "Bmal1 deficiency elevates fibrinolysis protease activity, triggering TGF‐β‐mediated expansion of α‐SMA+ myoCAFs that accelerate colorectal cancer (CRC) progression." (PMID 40772466, 2025). "BMAL1 also contributes to colorectal cancer metastasis by stimulating exosome secretion, providing insight into the role of circadian rhythms in cancer progression." (PMID 40243466, 2025). "This research explores the role of the Bmal1 gene in intestinal stem cell signaling and its impact on tumor initiation in colorectal cancer." (PMID 40589644, 2025). "This downregulation results in reduced cell motility, invasion, and drug resistance, suggesting a suppressive role of BMAL1 in maintaining an epithelial phenotype in colorectal cancer." (PMID 38361941, 2024). "Conversely, another study highlights a contrasting effect, revealing that the downregulation of BMAL1 strengthens the epithelial state of colorectal cancer cells." (PMID 38361941, 2024).
colorectal cancer (continued). "The dysregulation of BMAL1 in this context enhances the invasive potential of colorectal cancer cells, contributing to the metastatic cascade." (PMID 38361941, 2024). "For instance, CLOCK or BMAL1 can act as a tumor suppressor in prostate, breast, ovarian, and pancreatic cancers, but they promote tumor growth in colorectal cancer and acute myeloid leukemia." (PMID 39001398, 2024). "In colorectal cancer, BMAL1 plays a pivotal role in stimulating the migration and invasion of cancer cells." (PMID 38361941, 2024). "Taken together, these results suggested that BMAL1 increased the proliferation of colorectal cancer cells." (PMID 36806631, 2023). "Our recent study evaluated the c‐Myc and β‐catenin expression in cancer cell lines, confirming the activation of β‐catenin/c‐Myc signaling in BMAL1‐positive colorectal cancer cells." (PMID 36806631, 2023). "In this report, we provided evidence that increased BMAL1 expression in tumors promoted EMT‐like changes in colorectal cancer cell lines and lead to a dismal prognosis in patients with CRC." (PMID 36806631, 2023). "This study documented the malignant biological functions of BMAL1, such as increasing colorectal cancer cell metastasis and proliferation." (PMID 36806631, 2023). "Our report provides a new insight into the role of BMAL1 in colorectal cancer growth and metastasis." (PMID 36806631, 2023). "Western blotting analysis of Ki67 expression in colorectal carcinoma cells revealed that the level of the proliferation‐related protein Ki67 was significantly downregulated in the BMAL1 knockdown cell lines compared with the control cell lines (p < 0.05)." (PMID 36806631, 2023). "Karantanos T and colleagues proposed that the expression of BMAL1, a key clock gene, is more common in colorectal carcinomas, but less common in colorectal adenomas." (PMID 36806631, 2023). "In colorectal cancer, increased levels of BMAL1 have been related to decreased survival, and similarly, reduced levels of PER2 and PER3 have led to more inadequate tumor differentiation." (PMID 35356228, 2022). "Here, we used the human colorectal cancer (CRC) cell line HCT116 and its knockout variants for different core-clock genes (BMAL1, PER2, NR1D1), to investigate the treatment effect of C. cardunculus lipophilic leaf extract under different clock scenarios." (PMID 36012399, 2022). "Downregulated PER2 was associated with a higher likelihood of EMT in breast tissue, while downregulated BMAL1 decreased the invasion of mesenchymal cells in colorectal cancer." (PMID 35356228, 2022). "For example, the DNA alkylator temozolomide and the topoisomerase I inhibitor irinotecan have the maximum toxicity in glioblastoma and colorectal cancer during peak BMAL1 expression." (PMID 36291855, 2022). "In this report, we provided evidence, for the first time, that BMAL1-KD promotes mesenchymal-to-epithelial transition (MET)-like changes of colorectal carcinoma cell lines." (PMID 34065633, 2021). "In this study, we analyzed the consequences of circadian clock perturbation, specifically BMAL1-KD, on human colorectal cancer cell behavior." (PMID 32388500, 2020). "Overexpression of BMAL1 has also been shown to increase the responsiveness of colorectal cancer to oxaliplatin." (PMID 32231148, 2020). "BMAL1 overexpression increases the sensitivity of colorectal cancer cells to oxaliplatin by ATM pathway activation." (PMID 31014368, 2019). "Its influence on cancer cell behavior suggests that BMAL1 may be a promising therapeutic target in colorectal cancer." (PMID 40243466, 2025). "Similar in colorectal cancer, overexpression BMAL1 in cancer cell lines (HCT116 and SW620) could promote cancer cell distant metastasis." (PMID 38607733, 2024). "BMAL1 upregulation has been reported in various carcinomas, including colorectal cancer." (PMID 36806631, 2023). "Collectively, these evidences may prove that BMAL1 promotes the proliferate and migrate ability of colorectal cancer cell lines." (PMID 36806631, 2023).
colorectal cancer (continued). "The BMAL1/MAPK/c‐Myc signaling loop in colorectal cancer may represent a novel mechanism to regulate colorectal cancer growth." (PMID 36806631, 2023). "Plus, BMAL1 has been shown to facilitate the EMT in colorectal cancer." (PMID 37601651, 2023). "Additionally, BMAL1 has been shown to play antitumor roles in many human cancers, such as colorectal cancer, head and neck squamous cell carcinoma, and ovarian cancer 9-12." (PMID 36439870, 2022). "Indeed, high expression of BMAL1 increased the sensitivity to oxaliplatin and paclitaxel in colorectal cancer." (PMID 36291855, 2022). "In recent individual chronopharmacological studies, the DNA alkylator temozolomide and irinotecan, a topoisomerase I inhibitor, was shown to exhibit rhythmic drug toxicity in GBM and colorectal cancer cells, respectively, with maximum drug sensitivity occurring near the peak of BMAL1 expression." (PMID 34615982, 2021). "In line with this, it has recently been shown that PERK-mediated UPR activation led to temporal suppression of both Clock and Bmal1 and promoted cancer cell survival by attenuating protein synthesis, while the overexpression of Bmal1 sensitised colorectal cancer cells (CRCs) to chemotherapeutics." (PMID 30111611, 2018). "Interestingly, upregulation of Clock and CKIε expression was recently found in colorectal cancer tissues as compared to the adjacent normal mucosa and in these tissues the differential expression of Bmal1 and Per1 was correlated with metastasis." (PMID 24875049, 2014). "Additionally, Bmal1 deficiency in mice results in a decrease in Breg+ PDL1+ cell numbers among intestinal intraepithelial lymphocytes and induces the death of activated CD4+ T cells, thereby promoting the progression of colitis‐associated colorectal cancer." (PMID 38469551, 2024). "Taken together, BMAL1 regulated the activation of EMT process and the migration and invasion behavious of colorectal cancer." (PMID 36806631, 2023). "For example, the core circadian pathway members PER2 and BMAL1 serve as tumor suppressor in lung cancer, BMAL1 and CLOCK respectively act as tumor suppressor and oncogene in colorectal cancer, BMAL1 inhibits ferroptosis to increase the oncogenesis of acute myeloid leukemia." (PMID 38951864, 2024). "In the BMAL1‐negative colorectal cancer cell lines, the expression of these two oncogenes was significantly decreased." (PMID 36806631, 2023). "Furthermore, Bmal1 knockdown cooperates with heterozygous Apc deletion to induce WNT pathway hyperactivation, which upregulates c‐Myc expression and augments glycolytic metabolism, ultimately promoting colorectal cancer cell proliferation." (PMID 40772466, 2025). "These authors have found that high BMAL1 protein expression correlates to non-responsiveness to anti-angiogenic therapy with bevacizumab in mouse models of colorectal cancer and CRC patients and to poor clinical outcome in CRC patients following bevacizumab treatment." (PMID 33114496, 2020). "Here, we studied how BMAL1 knockdown (BMAL1-KD) by shRNA affects the epithelial–mesenchymal transition (EMT), a critical early event in the invasion and metastasis of colorectal carcinoma (CRC)." (PMID 34065633, 2021). "Whether these cancer stem cells are able to upregulate Lgr5 expression in a BMAL1 independent manner and how BMAL1, MEX3A and Lgr5 regulatory relationship in colorectal cancer stem cells differs from that in non-cancerous intestinal tissue will also be of interest for further investigation." (PMID 37845346, 2023).